BRCA2 (BRCA2 DNA repair associated)
Diseases named in the same sentence as BRCA2 in open-access papers (continued):
Sharing a sentence is not in itself a finding about the gene and the disease.
breast cancer (continued). "Based on its mutation frequency and disease penetrance, PALB2 is considered as the third major high-risk breast cancer gene alongside BRCA1 and BRCA2, all of which being key factors for the maintenance of genome stability." (PMID 38597967, 2024). "Factors that can increase the risk of breast cancer include age, genetic mutations (such as BRCA1 and BRCA2), family history of breast cancer, radiation exposure, obesity, etc.." (PMID 39247188, 2024). "EMSA was performed to check the DNA binding activity of MBD proteins on BRCA1, BRCA2, and p16 gene promoter in breast cancer." (PMID 38711004, 2024). "Researchers have targeted gene combinations such as BRCA1 and BRCA2, frequently found mutated in breast and ovarian cancer, and PARP1 and BRCA1, commonly mutated in breast cancer." (PMID 38195537, 2024). "One particularly noteworthy factor in hereditary breast cancer is the presence of pathogenic variants in the breast cancer susceptibility genes BRCA1 and BRCA2." (PMID 38167124, 2024). "Specifically, the study showed that surveillance with breast MRI detected 56% of breast cancers in BRCA1 mutation carriers and 73% in BRCA2 mutation carriers." (PMID 38791944, 2024). "It is part of an ongoing nationwide cohort established in 1997, which includes data from over 50 000 members of families with an increased risk of breast cancer and/or ovarian cancer, who were tested primarily for BRCA1 and BRCA2 genetic variants." (PMID 39384226, 2024). "BRCA1 and BRCA2 genes transheterozygosity is rare in the general population but is found to have a similar probability of developing breast cancer, ovarian cancer, or both cancers as compared to single mutations." (PMID 38903278, 2024). "While the risk of contralateral breast cancer in BRCA1 mutation careers decreases after menopause, incidence increases in BRCA2 mutation carriers." (PMID 38059556, 2024). "A genetic predisposition is observed in about 5–10% of breast cancers, and BRCA1 and BRCA2 are the most recognized mutations associated with a lifetime risk for breast cancer of 50–85% and 45–69%, respectively." (PMID 38656711, 2024). "The breast cancer cluster regions (BCCRs) within BRCA2 are identified at positions c.1–596, c.772–1806, and c.7394–8904." (PMID 38397209, 2024). "Recent molecular diagnostic studies have identified RECQL as an important breast cancer susceptibility gene, similar to BRCA1, BRCA2, and PALB2." (PMID 38439896, 2024). "Limited data are available regarding the partner and localizer of BRCA2 (PALB2) in Chinese patients with early breast cancer." (PMID 38914840, 2024). "Especially, the inherited risk for ovarian cancer associated with pathogenic variants in BRCA1 and BRCA2 is of clinical relevance and has a direct impact on the survival of women treated for BRCA1/2-associated breast cancers." (PMID 38491334, 2024). "The loss-of-function (LOF) classification of most missense variants in tumor suppressor breast cancer genes BRCA1, BRCA2, PALB2, and RAD51C remains unclassified and confounds clinical actionability." (PMID 39430403, 2024).
breast cancer (continued). "In patients with breast cancer, a high incidence of pathogenic variants of BRCA1 and BRCA2 is observed, as well as other highly mutated genes, such as PALB2, CHEK2, MUTYH, and ATM." (PMID 39335183, 2024). "On the one hand, the tumor-suppressing role of BRCA2 in breast cancer relies on the proper spatiotemporal formation of the BRCA2/PP2A-B56 complex." (PMID 38542160, 2024). "As in other Spanish population studies, the number of PVs was slightly higher in the BRCA2 gene than in the BRCA1 gene, and males with breast cancer in our study only had PVs in BRCA2." (PMID 39438962, 2024). "Upregulated expression of BRCA1 and BRCA2 genes was reported in BC and high BRCA1 gene expression was demonstrated to increase the risk of early distant metastasis in ER + breast cancer patients." (PMID 38165507, 2024). "To determine if the difference in these Wnt signaling genes can also be observed in other cancer types, we utilized a publicly available gene expression dataset for 4T1 BRCA1-null and 4T1 BRCA2-null mouse breast cancer cells." (PMID 39028933, 2024). "Recent comprehensive studies have highlighted that pathogenic variants (PVs) across eight distinct genes, such as ATM, BRCA1, BRCA2, CHEK2, PALB2 (FANCN), RAD51C, and RAD51D, exhibit a substantial correlation with breast cancer risk." (PMID 38397209, 2024). "Up to 10 % of hereditary breast cancer cases are usually associated with germline variants in BRCA1 and BRCA2 and more aggressive disease course." (PMID 39011181, 2024). "In this study, it was also found that the decrease in mRNA levels for several other key DNA repair proteins, including BRCA2 (Breast Cancer Gene 2), CHK1 (Checkpoint kinase 1), CHK2 (Checkpoint kinase 2), Rad51, and ATR, was caused by long-term exposure to Al." (PMID 39795956, 2024). "Breast cancer gene 1 (BRCA1) carriers are prone to lung and lymph node metastasis, while breast cancer gene 2 (BRCA2) carriers tend to have bone metastasis." (PMID 38586673, 2024). "This study elegantly demonstrates that a single metabolite, Methylglyoxal (MGO)—derived nonenzymatically from glyceraldehyde-3-phosphate mainly during glycolysis—can act as an oncogene by transiently inactivating Breast cancer type 2 (BRCA2)." (PMID 39239102, 2024). "Early breast cancer HER2-negative patients with high risk of recurrence should be tested for germline BRCA1 and BRCA2 mutations." (PMID 38869741, 2024). "The lifetime risk of developing breast cancer for carriers of BRCA1 and BRCA2 is estimated at 57–65% and 45–49%, respectively." (PMID 39484212, 2024). "Reduced expression of MLH1 in BRCA2-low tumor-induced DNA damage resulted in better breast cancer prognosis." (PMID 38271119, 2024). "Recently in breast cancer, some naturally occurring alternative transcripts of BRCA1 and BRCA2, through mutational variants in the splicing sites, have been found to encode protein isoforms with residual tumor suppressive activity." (PMID 39493168, 2024). "For BRCA2, the estimated breast cancer RR (95% CI) increased to a maximum of 14.1 (10.3–19.4) in the 40–49 age group and decreased to 4.9 (1.5–15.7) in the 70–79 age group (p-value for trend = 0.06)." (PMID 38333895, 2024).
breast cancer (continued). "More breast cancers were detected in BRCA1 carriers than in BRCA2 patients (1% RRM vs. 27% surveillance in BRCA1; 0% RRM vs. 19% surveillance in BRCA2)." (PMID 38248108, 2024). "AURKA can also interact and phosphorylate BRCA1 and BRCA2 genes, which are known to promote breast cancer when deregulated." (PMID 38886738, 2024). "It involves inheriting a mutation in key breast cancer genes such as BRCA1, BRCA2 etc, which increases breast cancer risk, although more education frequently leads to better access to healthcare resources and tests." (PMID 39610935, 2024). "The aimed to evaluate the impact of MBD proteins on the regulation of BRCA1, BRCA2, and p16 genes and their consequential effects on breast cancer cells." (PMID 38711004, 2024). "Germline pathogenic variants (PVs) in ATM, BRCA1, BRCA2, CHEK2, and PALB2 are detected in 5-7% of unselected women with breast cancer in the general population and are associated with a significantly increased risk of breast cancer in unaffected women." (PMID 39624521, 2024). "Breast cancer is indicated explicitly by genomic markers such as breast cancer susceptibility proteins (BRCA1 and BRCA2)." (PMID 39273572, 2024). "We focused on two high-frequency pathogenic mutations associated with hereditary breast cancer among Japanese patients—the BRCA1 Leu63Ter and the BRCA2 c.5576_5579delTTAA frameshift mutation." (PMID 38630824, 2024). "BET inhibitors have also been shown to be preferentially cytotoxic in the mutant BRCA2 context in both breast cancer and pan-cancer settings in a publicly available database for Genomics of Drug Sensitivity in Cancer." (PMID 39595558, 2024). "Our results from all-comers population genetic screening confirmed that rare pLOF variants in BRCA1, BRCA2, PALB2, ATM, and CHEK2 confer significant risk to breast cancer in the overall population." (PMID 39669587, 2024). "How cost-effective are ovarian and breast cancer risk reduction strategies among women with pathogenic variants in individual cancer susceptibility genes (ie, BRCA1, BRCA2, PALB2, RAD51C, RAD51D, and BRIP1)?" (PMID 38334999, 2024). "To perform this TWAS, we utilized summary statistics for ER + BC from the Breast Cancer Association Consortium (BCAC) and for ER- BC from a meta-analysis of BCAC and the Consortium of Investigators of Modifiers of BRCA1 and BRCA2 (CIMBA)." (PMID 38515142, 2024). "The study will enrol women, unaffected by cancer, undergoing predictive testing at a familial cancer clinic for a pathogenic variant in a known breast cancer (BC) or ovarian cancer (OC) predisposition gene (BRCA1, BRCA2, PALB2, CHEK2, ATM, RAD51C, RAD51D)." (PMID 39107016, 2024). "Risk management programs targeting women with genetic predispositions to breast cancer (BC), eg, BRCA1 and BRCA2, are effective assuming full adherence with the program protocol." (PMID 38564263, 2024). "In the American Cancer Society’s study of newly diagnosed breast cancer, 10% of patients had breast cancer gene 1 (BRCA1) and breast cancer gene 2 (BRCA2) mutations, whereas 35% of patients with TNBC carried a BRCA1 mutation, and 8% carried a BRCA2 mutation." (PMID 37513983, 2023). "Family history is a recognized significant risk factor for breast cancer (BC), with hereditary susceptibility attributed to mutations in genes like BRCA1 and BRCA2." (PMID 37888069, 2023). "Under normal circumstances, BRCA1 and BRCA2 are typical tumor suppressor genes, which means that people with BRCA1 and BRCA2 genetic defects are highly susceptible to breast cancer." (PMID 36765522, 2023). "Traditionally, genetic testing for breast cancer has been restricted to high-risk predisposition genes, such as BRCA1 and BRCA2." (PMID 37656691, 2023).
breast cancer (continued). "BRCA1 and BRCA2 mutations are found in around 10% of IBC diagnoses and confer a 5–10-fold increase in the odds of developing breast cancer." (PMID 37686673, 2023). "Deeper understanding of breast cancer family history based on genetics led to the discovery of the first major susceptibility genes for breast cancer (BRCA1 and BRCA2) over 20 years ago." (PMID 36749458, 2023). "Interestingly, although BC and OC are two different cancers that arise in different tissues of the body, women with breast cancer susceptibility gene type 1 and type 2 (BRCA1 and BRCA2) mutations have a higher risk of developing BC and/or OC." (PMID 37445860, 2023). "Our primary endpoint was to assess and compare the differences in ultrasonographic features between BRCA1 and BRCA2 breast cancers." (PMID 36905492, 2023). "Especially, our analyses indicate BRCA2 carriers a specific group of breast cancer patients, for whom the conventional prognostic estimation is not well-suited." (PMID 37173335, 2023). "Homologous recombination deficiency, such as that mediated by BRCA1 and BRCA2 (BRCA1/2) mutations, is associated with a high risk of breast cancer and ovarian cancer." (PMID 36717782, 2023). "BRCA2 (breast cancer 2, early onset) is one of the main mediators of RAD51 that activates RAD51 nucleofilament formation on ssDNA in HR and on replication forks." (PMID 37439366, 2023). "(LCS=322) studied the role of BRCA2-interacting protein called partner and localizer of BRCA2 (PALB2) in breast cancer." (PMID 37476378, 2023). "The P/LP variants most frequently associated with early onset hereditary breast cancer are those affecting the BRCA1 and BRCA2 (BRCA1/2) genes." (PMID 36971799, 2023). "Genetic predisposition accounts for 5–10% of all breast cancers, primarily attributed to pathogenic variants in BRCA1 and BRCA2 genes, responsible for nearly 90% of hereditary breast cancers." (PMID 38017478, 2023). "Distribution of VUS in breast cancer predisposing genes were :APC:1(5.8%), ATM:2(11.7%), BRCA1:1(5.8%), BRCA2:5(29.4%), BRIP1:1(5.8%), CDKN2A:1(5.8%), CHEK2:2(11.7%), FANC1:1(5.8%), MET:1(5.8%), STK11:1(5.8%), NF2:1(5.8%)." (PMID 37277882, 2023). "In the present work, we evaluated the associations of height, BMI, and change in weight with pre- and postmenopausal breast cancer risk for carriers of a pathogenic variant in BRCA1 or BRCA2, using data from the International BRCA1 and BRCA2 Cohort Consortium." (PMID 37340476, 2023). "We further provide population-specific evidence for the association of BRCA2 and ATM PTVs with overall breast cancer risk, and ER-negative breast cancer for PALB2 PTVs." (PMID 37790698, 2023). "Next-generation sequencing has led to the identification of prominent genes such as BRCA1 and BRCA2 involved in breast cancer initiation and progression." (PMID 37662839, 2023). "Supporting a role for BRCA1/2 in GBC, the Breast Cancer linkage consortium studied coincident cancers among 681 individuals with breast or ovarian cancer and 3047 carriers of BRCA1 or BRCA2 variants." (PMID 38163482, 2023). "There is ample evidence showing that the BRCA2 gene is closely related to the development and prognosis of multiple tumors, such as breast cancer, ovarian cancer and prostate cancer." (PMID 37355516, 2023).
breast cancer (continued). "Mutations in either of the type 1 or 2 breast cancer susceptibility genes (BRCA1 and BRCA2) account for the majority of hereditary breast cancers." (PMID 37176102, 2023). "Female BRCA1/2 PV carriers face a lifetime risk of roughly 70% for breast cancer (BRCA1: 95% confidence interval (CI) 65–79; BRCA2 95% CI 61–77)." (PMID 36767056, 2023). "Variants in key genes of HR, such as BRCA1, BRCA2, PALB2, BARD1, RAD51C, and RAD51D, which alter their function and/or their expression, have a significant association with breast cancer risk." (PMID 37372450, 2023). "For over two decades, genetic testing for women with an increased risk of breast cancer due to germline BRCA1 and BRCA2 mutations (gBRCAm) has allowed for better treatment planning, intervention, and long-term survival." (PMID 37623478, 2023). "These variants are closely related to high lifetime risk of developing HBOC; the reported cumulative lifetime risk of breast cancer is approximately 72% and 69%, up to the age of 80 years, for BRCA1 and BRCA2 respectively." (PMID 37055759, 2023). "In breast cancer, the figure of over 2% for the germline contribution of BRCA1 and BRCA2 is a justified estimate, as is 5.6% for all known variants (applicable to the populations used in the study)." (PMID 36882784, 2023). "In conclusion, our findings indicate that the associations of height, BMI and weight gain with breast cancer risk in BRCA1 and BRCA2 variant carriers are broadly similar to those reported in the general population when taking into account menopausal status." (PMID 37340476, 2023). "Recently, it has been reported that 13% of high-risk Cypriot breast cancer patients are positive for PVs in BRCA1 and BRCA2." (PMID 37790698, 2023). "This work advances understanding of the molecular functions of BRCA2 and, consequently, the molecular etiology of breast cancer in an important way." (PMID 36976771, 2023). "Another smaller study, including 44 breast cancer patients revealed the same pattern in the BRCA1 mutational prevalence; BRCA1 c.5266dupC and c.3607C>T, BRCA2 c.9371A>T were also prevalent in this group." (PMID 37239058, 2023). "Of 288 patients who developed breast cancer after being enrolled in the study, 19 (6.6%) carried BRCA1 P/LP (n = 8) or BRCA2 P/LP (n = 11) germline variants." (PMID 37628558, 2023). "In contemporary management, the most pertinent example illustrating the impact of genomic profiling on breast cancer surgery is the screening for pathogenic variants of the breast cancer gene 1 (BRCA1) and/or 2 (BRCA2)." (PMID 36753055, 2023). "To extend these findings, we investigated TSPAN8 and THRSP expression among the germline BRCA2-mutant tumours in the TCGA breast cancer dataset." (PMID 37626143, 2023). "The breast cancer mortality of BRCA2 carriers was underestimated at the low end of the PREDICT score distribution, whereas at the high end, the mortality was overestimated." (PMID 37173335, 2023). "In BRCA1 or BRCA2 mutants, these errors result in chromosomal rearrangements and shifts that are characteristic of hereditary breast cancer." (PMID 37241036, 2023). "Protein-truncating variants in BRCA2 were the most prevalent in our study (1.82%), with the founder BRCA2 c.8756delG PTV being detected in ten breast cancer cases (1.01%) which corresponds to more than half of the BRCA2 PTVs observed among cases." (PMID 37790698, 2023). "In breast cancer, some of the mutations are inherited breast cancer gene 1 and 2 (BRCA1, BRCA2), but most of them are acquired during the lifetime due to environment and lifestyle exposure or after chemotherapy." (PMID 36675137, 2023). "In a previous study, we demonstrated that AZD2281 (olaparib) inhibits cell viability and induces autophagy/mitophagy in BRCA1- and BRCA2-mutant breast cancer cell lines." (PMID 37509303, 2023). "For example, the genetic sequencing of patients at high risk for breast cancer in the United States has identified BRCA1 and BRCA2 as strong genetic markers." (PMID 37113463, 2023).